RNF5 (ring finger protein 5)
Diseases named in the same sentence as RNF5 in open-access papers (continued):
Sharing a sentence is not in itself a finding about the gene and the disease.
RNF5 also shares sentences with these, for which no sentence is quoted: hepatocellular carcinoma (4 papers); glioma (2); lung carcinoma (2); cognitive decline (1); distal myopathy (1); gastritis (1); heart failure (1); herpes simplex virus keratitis (1); muscle disorders (1); Neuroectodermal Tumors (1); nonalcoholic steatohepatitis (1); spondyloarthritis (1); T-cell acute lymphoblastic leukemia (1); toxoplasmosis (1); ulcerative colitis (1); viral diseases (1).